CA12 (carbonic anhydrase 12)
Diseases named in the same sentence as CA12 in open-access papers (continued):
Sharing a sentence is not in itself a finding about the gene and the disease.
cancer (96 papers, 2003 to 2025). A tumor composed of atypical neoplastic, often pleomorphic cells that invade other tissues. "Out of the twelve human CAs, two membrane associated CA isoforms–CA9 and CA12 have been largely implicated in cancer development, particularly in case of solid cancers." (PMID 38530845, 2024). "Plasma membrane-associated carbonic anhydrases 12 (CA12) can be considered as a cancer cell surface marker and exhibits a significant relationship in various cancers, such as breast cancer." (PMID 31546841, 2019). "We identified Carbonic Anhydrase 12 (CA12) as a significant RNAseq-based biomarker, closely associated with the NF-κB survival signaling pathway, which is crucial in cancer cell response to oxidative stress." (PMID 38515178, 2024). "We assessed the mRNA expression levels of LRRC15, EFNA3, TSPAN13, and CA12 in diverse cancer tissues and compared them to normal tissue using the TIMER2.0 database." (PMID 38611080, 2024). "Taken together, these findings suggest that LRRC15, EFNA3, TSPAN13, and CA12 can serve as potential biomarkers for improving cancer diagnosis screening and as suitable targets for therapy with reduced side effects and enhanced efficacy." (PMID 38611080, 2024). "Second, CA12 regulates extracellular pH, which plays a role in important cancer processes including invasion and metastasis." (PMID 28304380, 2017). "Importantly, the overexpression of LRRC15, EFNA3, TSPAN13, and CA12 was observed in tissues at both early and advanced stages of cancer, indicating that these proteins hold promise as targets for early diagnosis." (PMID 38611080, 2024). "Of the CA isoforms, only CA9 and CA12 are highly expressed in cancer tissues and therefore may contribute to the acidification of the extracellular milieu." (PMID 30863491, 2019). "Carbonic anhydrase XII (CA12) expressed in TAMs stimulates the production of significant quantities of CCL8, which promoted cancer cell EMT." (PMID 37663266, 2023). "In the results of the current series of RNAseq analyses, Adam8, CA12, and CDH6 were identified as candidates for myCAF-induced cancer-stemness-related genes with secreted proteins." (PMID 37370863, 2023). "Although CA12 is not regulated by hypoxia, along with CA9, CA12 represents another membrane associated CA implicated in cancer development." (PMID 38530845, 2024). "The lack of efficacy of compounds 1, 2 and 4 in ca12 KO cancer cells further demonstrated that CAXII inhibition is the critical mechanism of action in reversing doxorubicin resistance." (PMID 27811376, 2016).
Neurological Disease (1 paper, 2015). "The most prominent pathway identified by IPA analysis indicated that this cluster was enriched in "Neurological Disease"-related genes (Adcyap1, Bdnf, CA12, Cdkn1a, Vgf)." (PMID 25803291, 2015).
CA12 also shares sentences with these, for which no sentence is quoted: melanoma (7 papers); lung carcinoma (6); brain tumors (4); cervical carcinoma (4); colorectal cancer (4); invasive breast carcinoma (4); renal cell carcinoma (4); invasive carcinoma (3); triple-negative breast carcinoma (3); adenocarcinoma (2); glial tumours (2); glioma (2); ovarian carcinoma (2); squamous cell carcinoma (2); adenoma (1); adrenocortical carcinomas (1); astrocytomas (1); breast ductal carcinoma in situ (1); colon adenocarcinoma (1); colon adenoma (1); COVID-19 (1); diffuse astrocytoma (1); epilepsy (1); esophageal cancer (1); fibrolamellar carcinoma (1); glaucoma (1); Granuloma (1); gynecological tumors (1); Hodgkins lymphoma (1); Hyponatremia (1).
A further 21 diseases each share a sentence with CA12 in 1 paper.